PPARG (peroxisome proliferator activated receptor gamma)
Diseases named in the same sentence as PPARG in open-access papers (continued):
Sharing a sentence is not in itself a finding about the gene and the disease.
tumor (continued). "Thus we hypothesize that estrogen helps tumor cell survival and growth by interfering with PPARγ-mediated apoptosis at multiple steps in the biosynthesis of its ligand." (PMID 17407572, 2007). "Moreover, PPARγ could suppress β-catenin levels and colon carcinogenesis during the early steps of tumor formation." (PMID 15892897, 2005). "In summary, we identify a TRIM28-PPARG SUMO-ubiquitin crosstalk axis that drives metabolic remodeling and tumor growth in BLCA, highlighting TRIM28-mediated PPARG SUMOylation as a potential therapeutic target for metabolic intervention." (PMID 41974657, 2026). "The high stiffness of the tumour ECM activates Piezo1 in macrophages, triggering the STAT6/PPARγ signalling pathway, which promotes M2 polarization and suppresses anti-tumour immunity." (PMID 41437911, 2026). "YTHDF3 translates m6A-rich transcripts and promotes brain metastasis of tumors; FTO regulates the stability and expression of PPARγ and C/EBP-α/β mRNA, and promotes tumor growth and lung metastasis." (PMID 41446042, 2025). "4OI exerted tumor promoting effects in both cancer cell lines by downregulating NFKB and PPARG in coculture with either M0 or M2 macrophages." (PMID 40552282, 2025). "The signaling lipids produced by FABP5 and monoacylglycerolase (MAGL) enter the nucleus and bind to receptors such as PPARγ to regulate VEGF factor synthesis and promote tumor metastasis." (PMID 41281744, 2025). "Mechanistically, CD36 exerts its tumor‐suppressive effect by regulating the expression and activity of CAV1 via PPARγ, which increases intracellular lipid peroxidation and promotes ferroptosis in TNBC cells." (PMID 41267927, 2025). "Among them, seven cancer genes (ERBB2, ERBB3, PPARG, MYC, CCND1, CCNE1, MDM2) were detected to be amplified in both ctDNA and tumor tissues, indicating the reliability of ctDNA in reflecting the genomic features of tumors." (PMID 40191434, 2025). "Furthermore, alterations in tumor glycolysis are also associated with changes in intracellular signaling pathways induced by various oncogenes or tumor suppressor genes, such as long non-coding RNA Ftx, which promotes aerobic glycolysis and tumor invasion in HCC by inducing the PPARγ pathway." (PMID 39980550, 2025). "In medulloblastoma models, EA further targets and inhibits the Shh signaling-driven E2F1/PPARγ axis, reducing the expression of key glycolytic enzymes (e.g., HKII, PKM2) and impairing glucose uptake efficiency, ultimately suppressing tumor cell proliferation." (PMID 40823021, 2025). "For instance, low PPARG expression correlated with clinicopathological parameters such as macroscopic vascular invasion and TNM (tumor, node, metastasis) stage in HCC patients." (PMID 41148824, 2025). "As a downstream effector of peroxisome proliferator-activated receptor γ (PPARγ), Gal-9 inhibits key steps in tumor progression, including ECM invasion, cellular detachment from the primary tumor, and adherence to the vascular endothelium." (PMID 40710343, 2025). "Moreover, in the tumor microenvironment and immune compartments, PPARγ exerts highly variable effects, modulating inflammation, differentiation, and metabolism in ways that may either support or suppress cachexia progression, depending on cancer type and inflammatory milieu." (PMID 41476922, 2025). "Focusing on specific PPAR pathway receptors, we observed PPARG and PPARD upregulation in PC tumor tissue samples in the TCGA cohort." (PMID 40860798, 2025). "Interestingly, PPARγ activity may also affect anti-tumor immune surveillance and responses." (PMID 40931013, 2025). "miR-27b, which is overexpressed in BCa, has been shown to inhibit PPARγ and vitamin D receptor (VDR) in glioblastoma, reducing tumor progression." (PMID 40806474, 2025).
tumor (continued). "Clinically, TNBC tumor tissues displayed notable down-regulation of FABP4 and PPARG in comparison with normal tissues." (PMID 40604951, 2025). "In contrast, mutant TRβ exerts a dominant-negative effect over PPARγ; it retains DNA-binding ability, competes for PPRE occupancy, and disrupts transcriptional activation of tumor-suppressive programs." (PMID 41153831, 2025). "PPARγ, a key regulator of lipid metabolism, directly binds to the ACSL4 promoter, and its de-repression by BQ amplifies FAO, fueling tumor growth and proliferation." (PMID 40507798, 2025). "Upon activation by ω-3 LCPUFAs, PPARγ directly affects the NF-κB pathway and downregulates the level of pro-inflammatory factors such as MCP-1, IL-6, and TNF-α, so as to suppress neoplasia development." (PMID 39834867, 2025). "In contrast, dioscin exerts dual anti-inflammatory and anti-tumor activity through mTORC1/HIF-1α inhibition and PPARγ activation, showing broader applicability in both colitis and melanoma." (PMID 40417220, 2025). "As expected, PPARγ and GPX4 levels were lower in the GW9662-treated tumor tissues than in the control tumors." (PMID 38786003, 2024). "Moreover, PPARγ has been recognized as a crucial agent in the process of adipocyte differentiation, lipid storage, and glucose metabolism, all of which play a significant role in creating the tumor microenvironment and facilitating the survival of cancer cells." (PMID 39148124, 2024). "Specifically, AKT2 exhibited significant overexpression in tumor tissue (p = 0.01), while AKT2, AKT3, PPARG, and PTEN displayed significant increases in normal tissue (p ≤ 0.04)." (PMID 38505269, 2024). "In tumor samples, PPARD and PPARG were correlated with EMT-related pathways and proliferation-related pathways, respectively." (PMID 38529307, 2024). "Treatment with PPARγ inhibitors in an in vitro OSCC model resulted in a substantial increase in the number and proportion of cDCs and CD8+ T cells in tumor tissue, leading to a significant inhibition of tumor growth." (PMID 38786003, 2024). "We analyzed the effect of SYF treatment on the protein expressions of VEGFR2, PPARγ, and SOD1 in TNBC cells and tumor tissues." (PMID 38516703, 2024). "The tumor cells from the endometrium, esophagus, thyroid, and kidneys show dominant expressions of receptors like RXRA (Retinoid X Receptor Alpha), RXRB, PPARG, and ADORA1 (Adenosine A1 Receptor), underscoring their diverse physiological roles." (PMID 39766077, 2024). "BHLHE40 has been reported to have tumor suppressive functions and has been shown to affect energy metabolism by regulating PGC-1α, SREBP-1c, PKLR, PCK2, FASN, and PPARγ." (PMID 38301894, 2024). "TNF (p = 0.0284), PPARG (p = 0.0379) and ESR1 (p = 0.0268) were significant in tumor staging in GC patients." (PMID 37171392, 2023). "The lipid mediators produced by eLOX3/ALOXE3, including 12-oxo-ETE, have anti-tumor effects, particularly 12-oxo-ETE, which is a ligand for PPARγ." (PMID 36765904, 2023). "For instance, cluster 10 showed a tumor-promoting role as indicated by the high expression of EZH2, and cluster 0 had high expression level of the transcription factor PPARG that can regulate the production of M2-like macrophages." (PMID 37644609, 2023). "When capsaicin is administered to human GBM LN-18 cells, peroxisome proliferator-activated receptor gamma is expressed, facilitating GBM tumor cell apoptosis." (PMID 37241023, 2023).
tumor (continued). "CDK inhibitors hold immense promise in halting tumor development, progression, and metastasis, mediated through diverse pathways such as CDK5–FAK, PPARγ, PP2A, Hippo, and Wnt/β-catenin, among others." (PMID 37887415, 2023). "In contrast, PPARγ agonists restored CD8+ Teffs pools, potentiated vaccine-driven anti-tumor response in combination with CTLA4 Ab in vivo, and reduced chemokine expression in tumor cell co-cultures with human peripheral blood mononuclear cells in vitro." (PMID 37686465, 2023). "One example of a proliferation inhibitor is peroxisome proliferator-activated receptor-gamma (PPAR-γ), a nuclear receptor that regulates cell-cycle arrest and apoptosis in tumor cells." (PMID 37681858, 2023). "Tumor macrophages expressed higher levels of CD68 and PPARγ and lower levels of HLA-DR compared to components that resided in adjacent tissues." (PMID 35874784, 2022). "However, in breast cancer, the truncated PPARγ caused by capspace-1 mediated cleavage could attenuate MCAD activity and inhibit FAO; as a result, the consequent lipid droplet accumulation in TAM promoted the differentiation of TAMs to a pro-tumor phenotype." (PMID 35392570, 2022). "In the setting of cancer, PPARγ activation was shown to reverse the MDSC and M2 macrophage-mediated suppression of the cytotoxic T lymphocyte (CTL) anti-tumor responses." (PMID 35954274, 2022). "This suggests a loop or synergy between the action of metformin and EPA that decreases inflammation and inhibits tumor growth by activating AMPK and other common mediators such as PPARγ." (PMID 35326656, 2022). "The inhibition of PPARγ by inverse agonists inhibits MEC cell proliferation and tumor growth in xenograft models." (PMID 35954274, 2022). "Whether PPARγ agonists sensitize NSCLCs to chemotherapy and are of therapeutic benefit, or whether other Hif-1α-dependent signaling pathways might interfere in this tumor type, could be relatively easily answered from researchers’ long clinical experience with the use of PPARγ agonists." (PMID 35954274, 2022). "Each of the LEP, NOTCH1, SPRY1, PPARG, ID2, and CIDEA genes is also involved in tumor development in humans." (PMID 35395810, 2022). "Simultaneous PPARγ activation and MEK inhibition combines the two therapy steps, tissue editing and targeted therapy in the edited tumor tissue." (PMID 35814409, 2022). "We performed immunohistochemical analysis on tumor samples, for relevant gene-expression-based markers for basal type (CD44, CK5/6) and luminal type (CK20 and pPARγ)." (PMID 35805028, 2022). "PPARG (PGD2 and PGE2 metabolites, 15-HETE) expression is widespread and can be found in tumor cells, myeloid cells, stellate cells, and endothelial cells, with minor expression in several other cell types." (PMID 36277993, 2022). "Recent study has found that ILC2s in human and mouse CRC express PPARγ, which maintains ILC2 secretion of IL-5 and IL-13 and the pro-tumor effect of ILC2s." (PMID 35720302, 2022). "To further explore the function of PPAR signaling pathway in tumorigenesis, we treated tumor-derived organoids with the drug FH535, which is a Wnt/β-catenin signaling pathway inhibitor and a dual PPARγ and PPARδ antagonist." (PMID 35974387, 2022). "Then, we picked out 8 HAIRGs (VEGFA, CTNNB1, PPARG, HSP90AA1, HMOX1, LGALS3, SPP1, and RAC1) from the 17 HAIRG model through the LASSO Cox regression, upregulated genes accounted for 7/8 in tumor tissue, which was shown by a heat map." (PMID 35069936, 2022). "Moreover, the PPAR signaling pathway was prevalently and aberrantly activated in tumor cells and inhibition of this signaling pathway through PPARγ inhibitor could both dramatically suppress the growth and accelerate the apoptosis of the tumor epithelial cells." (PMID 35974387, 2022). "On the contrary, PPARγ is considered a tumor suppressor that reduces the CD49high/CD24+ mesenchymal stem cells (MSCs) and inhibits tumor angiogenesis of breast cancer." (PMID 36226253, 2022).
tumor (continued). "They revealed a tumor-specific depletion of CD8+ T effector cells and the tumor-enriched macrophages with the expression of PPARγ potentially contributing to immune suppression in TME." (PMID 34177965, 2021). "The hypoxic TME further aggravates the autophagic phenotype in tumor stromal cells, suggesting a modifying role of hypoxia-inducible factor 1α (HIF-1α) in PPARγ-dependent autophagy." (PMID 33946986, 2021). "The effect of PPARG driven AKT3 up-regulation results in an accumulation of PGC1α, which drives mitochondrial biogenesis and tumour growth and development." (PMID 33654198, 2021). "In an esophageal epithelium cell carcinogenesis model, α-TF reduced cell proliferation and increased PPARγ expression, along the downstream PTEN tumor suppressor, acting as a PPARγ agonist." (PMID 33919211, 2021). "The tumor-derived Wnt5 ligand can activate β-catenin signaling in TADC, which upregulates PPARγ to induce Carnitine Palmitoyltransferase 1A (CPT1A)-driven FAO in a murine melanoma model." (PMID 34988072, 2021). "A systematic bioinformatic appraisal of PPARγ and DNMT1 was performed across 29 tumor types and UM available in The Cancer Genome Atlas (TCGA)." (PMID 34439147, 2021). "Analyses of two microarray datasets (GSE109169-GSE89116) have revealed differential expression of PPARG and SQLE genes in EOBC tumor tissues (<40 years) compared to normal breast tissues." (PMID 33807872, 2021). "Our subsequent experiments showed that miR-130a/b suppresses PPARG expression in RD cell lines, indicating that it can promote RMS development as a tumor promoter." (PMID 35187064, 2021). "CCL18+M1, CXCL9+M2, and TIMP1+M3 were enriched in tumor tissues and were regarded as TAMs, whereas SELENOP+M4, MMP7+M5, CHIT1+M6, and PPARG+M7 were enriched in normal tissues and considered as resident tissue macrophages (RTMs)." (PMID 34659209, 2021). "Actually, previous researchers have identified lncRNAs as prognostic markers of PTC, such as TTTY10, LINC00284, RBMS3-AS1, and ZFX-AS1 and five lncRNAs of PPARG, E2F1, CCND1, JUN, and EZH2 for predicting tumor recurrence in PTC." (PMID 34721037, 2021). "The lowest PPARG expression was observed from an HSCC patient in a stage of T4aN0M0, which means that the tumor size and extension of the primary tumor were at the late stage, but with no influence on regional lymph nodes and no metastasis." (PMID 34054937, 2021). "Only a few macrophage genes such as PPARG, MSR1/CD204, and MARCO were downregulated in TAMs compared to non-tumor macrophages in our dataset." (PMID 33918618, 2021). "In contrast, mRNA levels of PPARγ and SCAP, which participate in the control of lipid synthesis in intestinal crypts, were both reduced in tumor cells." (PMID 34206240, 2021). "Tumours derived from clone OE19 showed elevated AKT3, PGC1a and VDAC1 confirming the effect of PPARG on this pathway." (PMID 33654198, 2021). "Consistently, PIO, the agonist of PPARγ, successfully restored SREBP1 expression, cholesterol synthesis, and IFN-γ production in human tumor-infiltrating iNKT cells." (PMID 31974378, 2020). "PPARγ inhibited tumor proliferation and metastasis by inhibiting LEF1/β-catenin signaling, and the expression of PPARγ in UC after RT decreased significantly." (PMID 33289586, 2020). "Reduction of PPARγ and IFN-γ was observed in tumor-infiltrating iNKT cells in both human patients and mouse models." (PMID 31974378, 2020). "Pearson's correlation analysis showed a significantly positive correlation between pho‐PPARγ and CDK5 in the tumor tissues (Pearson r = 0.5195, p < 0.001)." (PMID 33240752, 2020). "The least distinct differences in POX, PPARγ and HIF1-α expression were found in the group of highly differentiated tumours (G1, KI-67 < 40%)—The average expression of PRODH/POX and PPARγ was 88% compared to normal tissue, while HIF1α was 130%." (PMID 31935820, 2020).
tumor (continued). "To confirm the results from public datasets, we examined PPARγ expression in GBM patient tissues, where two pairs of normal and corresponding tumor samples prospectively and six paraffin embedded tumor tissues retrospectively were obtained." (PMID 32280134, 2020). "PPARγ expression was dramatically upregulated in GBM tumors compared to the corresponding normal tissues in the two patients, and the tumor tissues showed CD44-positive expression, indicating an MES subtype." (PMID 32280134, 2020). "FAS and MAGL’s roles in promoting tumor metastasis in PCa are critically dependent on FABP5, which induces PPARγ transcriptional activity, pointing to a role for the FABP5-PPARγ pathway in mediating fatty acid-induced metastasis in these tumors." (PMID 33352874, 2020). "The least distinct differences in POX, PPARγ and HIF1-α expression occurred in the group of highly differentiated tumours (G1)." (PMID 31935820, 2020). "The most significant differences in the expression of selected proteins were observed in the group of poorly differentiated tumours (G3, KI-67 > 70%): the mean value of PRODH/POX expression was 52% compared to normal tissue, 48% of PPARγ, and 163% of HIF-1α." (PMID 31935820, 2020). "The PPARγ agonist rosiglitazone increased micro RNA miR-15a expression which inhibited angiopoietin-1, resulting in decreased angiogenesis, MSC expansion, and tumor growth in vivo." (PMID 32785018, 2020). "In comparison with splenic iNKT cells, tumor infiltrating-iNKT cells reduced IFN-γ, PPARγ, SREBP1, and cholesterol." (PMID 31974378, 2020). "Double-labeling of vessels for PPARγ and proliferating nuclear antigen (PCNA) revealed significantly reduced endothelial cell proliferation in the tumor specimens from animals which received rosiglitazone." (PMID 32785018, 2020). "UHRF1 is also associated with epigenetic silencing of various tumor suppressors and other tumor-related genes, including CDKN2A, RB, BRCA1, RASSF1, PPARG, APC, CDH1, and RGS2." (PMID 31064417, 2019). "A tissue microarray (TMA) was constructed from tumor specimens in triplicate and stained by immunohistochemistry for RET, phospho‐MEK, MAPK(dpERK), PPARγ, and phospho‐AKT(pAKT)." (PMID 30552739, 2019). "In this work we have shown that the treatment of PC3-M cells with the PPARγ antagonist, GW9662, produces a suppression of tumour growth similar to that obtained with dmrFABP5." (PMID 31258834, 2019). "Cardiolipin, a phospholipid, promotes IL-10 expression in MDSCs from the lungs of tumor-bearing mice by activation of PPARγ activity but this can be inhibited by GW9662 (a specific inhibitor of PPARγ)." (PMID 31275326, 2019). "Despite the conflicting views regarding the effect of PPARs on cancer, the agonistic effect on PPARγ by ASX treatment leads to the inhibition of growth and cell cycle as well as an induction of apoptosis against several tumor cells." (PMID 31018521, 2019). "The PPARγ-agonistic effect of ASX treatment results in the inhibition of cellular growth and apoptosis in tumor cells." (PMID 31018521, 2019). "The PTEN gene promoter is a known target for PPARγ, which has been shown to induce PTEN expression in inflammatory and tumor-derived cells." (PMID 30148676, 2019). "PPARγ overexpression inhibits the activity of TNF-α and NFκB resulting in a reduction of tumor development." (PMID 29706964, 2018). "We previously showed that PPARγ, another member of the PPAR superfamily, is involved in tumor progression." (PMID 29862267, 2018). "A recent study has reported that PPARG controls prostate cell growth and differentiation and is involved in androgen-dependent PCa and CRPC evolution, acting as a tumor suppressor through its interplay with AR." (PMID 29966326, 2018). "In this work we showed that the treatment of PC3-M cells with the PPARγ antagonist, GW9662, produced a better suppression of tumour growth to that obtained by SBFI26." (PMID 28415688, 2017).